SLITRK3 (SLIT and NTRK like family member 3)
Description:
Suppresses neurite outgrowth.
Synonyms: KIAA0848
Tractability: Antibody: its Gene Ontology location is reachable by antibodies, with high confidence; UniProt predicts a signal peptide or a membrane-spanning region. PROTAC: its protein half-life has been measured.
Gene: Protein-coding gene on chromosome 3 (165,186,325 to 165,197,109, reverse strand). Ensembl gene ENSG00000121871.
Subcellular location: Membrane
Subcellular location (Human Protein Atlas): Mitochondria
Pathways (Reactome):
Neuronal System: Receptor-type tyrosine-protein phosphatases
Signal Transduction: RAC3 GTPase cycle
Gene Ontology:
Molecular function: protein binding
Biological process: regulation of presynapse assembly; synaptic membrane adhesion; axonogenesis; positive regulation of synapse assembly
Cellular component: GABA-ergic synapse; postsynaptic specialization membrane; plasma membrane; postsynaptic density membrane; cell surface; membrane; postsynaptic membrane
Genetic constraint (gnomAD): Loss-of-function variants: 16 observed, 66.79 expected, observed/expected ratio (o/e) 0.24, 90% interval 0.16 to 0.36. The upper end of that interval is the gene's LOEUF score, 0.36, which puts it in group 1 of 6, group 1 being the genes least tolerant of losing a copy. Missense variants: 1,117 observed, 1,246.5 expected, observed/expected ratio (o/e) 0.9, 90% interval 0.85 to 0.94. Synonymous variants: 547 observed, 478.79 expected, observed/expected ratio (o/e) 1.14, 90% interval 1.06 to 1.23.
Homologues: Orthologues: chimpanzee SLITRK3 (99% identical), macaque SLITRK3 (99% identical), dog SLITRK3 (99% identical), rabbit SLITRK3 (99% identical), pig SLITRK3 (97% identical), mouse Slitrk3 (96% identical), rat Slitrk3 (96% identical), guinea pig SLITRK3 (94% identical), tropical clawed frog slitrk3 (77% identical), zebrafish slitrk3a (70% identical). Paralogues in human: SLITRK5 (40% identical), SLITRK2 (38% identical), SLITRK4 (35% identical), SLITRK6 (32% identical), SLITRK1 (27% identical), SLIT3 (16% identical), SLIT1 (15% identical), SLIT2 (15% identical), TLR9 (14% identical), LRRN1 (13% identical), LRRC70 (13% identical), LRRN2 (12% identical), and 13 more.
Diseases named in the same sentence as SLITRK3 in open-access papers:
SLITRK3 is named in the same sentence as 24 diseases in open-access papers, as found by Europe PMC text mining. Sharing a sentence is not in itself a finding about the gene and the disease. The quoted sentences say what the papers report.
brain tumor (2 papers, 2016 to 2021). "In our own lung metastatic brain tumor sample set, SOX2 was not among genes focally amplified according to GISTIC analysis, but tumors with SLITRK3 amplification displayed SOX2 copy number gains (data available at GSE157515)." (PMID 35006496, 2021).
steatosis (2 papers, 2020 to 2024). Increased lipid within the cytoplasm of cells. "We also found the expression of SLITRK3 (SLIT and NTRK like family member 3) was down-regulated in steatosis and NASH patients." (PMID 33324350, 2020). "Of the top-ranked 10 genes, two genes (CYP7A1 and PEG10) were significantly up-regulated in both steatosis and NASH patients, while eight genes (FOSB, FOS, IL6, GADD45G, MYC, SLITRK3, JUNB, and IGFBP2) were significantly down-regulated." (PMID 33324350, 2020).
Anxiety (1 paper, 2024). Intense feelings of nervousness, tension, or panic often arise in response to interpersonal stresses. "Furthermore, reduced PV interneurons in SLITRK3 KO dentate gyrus could explain their hyperactivity and reduced anxiety-like behaviors because optogenetic activation of the dentate gyrus granule cells increases locomotive activity and open arm stayed time in elevated plus maze test." (PMID 38495551, 2024).
developmental epileptic encephalopathy (1 paper, 2024). "We identified de novo heterozygous and bi-allelic mutations in SLITRK3 in 5 individuals from 3 families, with a developmental epileptic encephalopathy phenotype." (PMID 38495551, 2024).
endometriosis (1 paper, 2025). The growth of functional endometrial tissue in anatomic sites outside the uterine body. "Furthermore, the identification of upregulated genes, such as SIRT1, SBDS, SRF, SPN, P2RX1, TEAD3, and SLITRK3, alongside downregulated genes, including KIF22, KIF25, GAS2L2, and HINT3, highlights a broad transcriptional reprogramming within endometriosis-affected tissues." (PMID 41516028, 2025).
epilepsy (1 paper, 2024). A brain disorder characterized by episodes of abnormally increased neuronal discharge resulting in transient episodes of sensory or motor neurological dysfunction, or psychic dysfunction. "Our data have now revealed that epilepsy-associated human mutations in SLITRK3 disrupt its function in regulating GABAergic synapses, leading to a number of neurological consequences in human patients." (PMID 38495551, 2024).
Epileptic encephalopathy (1 paper, 2024). A condition in which epileptiform abnormalities are believed to contribute to the progressive disturbance in cerebral function. "In this study, we report on biallelic and monoallelic variants in SLITRK3 in three families presenting with epileptic encephalopathy associated with neurodevelopmental findings that include seizures, motor delay, microcephaly, hyperactivity, and MRI brain abnormalities." (PMID 38495551, 2024).
gastrointestinal stromal tumor (1 paper, 2020). "SLITRK3 (SLIT And NTRK Like Family Member 3) is expressed predominantly in neural tissues with neurite-modulating activity, in hematopoietic stem cells and leukemias, and correlates to gastrointestinal stromal tumor risk rating and prognosis." (PMID 33072755, 2020).
Intellectual disability (1 paper, 2024). "In addition, the cognitive dysfunction observed in SLITRK3 KO mice might pinpoint to the physiological function of the protein, as similar manifestations of sensory/motor signs or intellectual disability were present in the three siblings with the SLITRK3 nonsense mutation." (PMID 38495551, 2024).
cancer (4 papers, 2016 to 2022). A tumor composed of atypical neoplastic, often pleomorphic cells that invade other tissues. "Although expressions of 9 hyper-methylated genes were significantly different across cancer stages in the TCGA cohort, reduced expressions with increased cancer severity were observed for 3 hyper-methylated genes- SLITRK3, FOXE1, and TWIST1." (PMID 36329447, 2022). "Based on a recent literature search, this is the first report of a mechanistic role for SLITRK3 in cancer." (PMID 35006496, 2021). "Addressing this need, the current report introduces the novel cancer gene SLIT- and NTRK-like family member 3 (SLITRK3) and its role in activating the neurotrophic receptor tyrosine kinase 3 (NTRK3) in LUSC cells." (PMID 35006496, 2021). "Results provide evidence that SLITRK3 gene amplification frequently occurring in LUSC causes aberrant SLITRK3 overexpression and facilitates SLITRK3-dependent ligand activation of NTRK3 to induce a cancer stem cell (CSC) phenotype." (PMID 35006496, 2021). "Altogether, the results indicate that gene amplification and consequent high expression of SLITRK3 in LUSC is associated with worse outcomes and induces SLITRK3-dependent activation of NTRK3 to promote a cancer stem cell phenotype that is inhibited by existing NTRK-targeted inhibitors." (PMID 35006496, 2021). "The results included well-known cancer genes such as MYC, FOXA2 and FADD, and the unknown SLITRK3 gene." (PMID 35006496, 2021). "SLITRK3 is up-regulated in many cancers, including gastrointestinal cancer, and there is no clear information available about its association with NAFLD and NASH." (PMID 33324350, 2020).
tumor (2 papers, 2021 to 2022). "Lastly, GALR1 has also been documented to multiple correlations with tumour stages, lymph node status and the expression levels of SLITRK3 and SIGIRR genes." (PMID 36329447, 2022). "We plan to extend these findings in future work using LUSC patient tumor samples to examine if NTRK3 detection correlates with SLITRK3 amplification and high levels of lung CSC markers, such as CD133 or ALDH1." (PMID 35006496, 2021). "Furthermore, SLITRK3 amplification recurring in LUSC at a frequency of 30% with the mechanistic role we have uncovered can explain why a previous tumor immunostaining study reported NTRK3 protein is absent in LUAD samples but detected in approximately 30% of LUSC samples." (PMID 35006496, 2021).
neurological diseases (1 paper, 2024). "SLITRK3 encodes for a transmembrane protein that is involved in controlling neurite outgrowth and inhibitory synapse development and that has an important role in brain function and neurological diseases." (PMID 38495551, 2024).
SLITRK3 also shares sentences with these, for which no sentence is quoted: psychiatric diseases (2 papers); Ataxia (1); brain disorder (1); Cirrhosis (1); cognitive disorder (1); developmental delay (1); Dystonia (1); leukemia (1); lymphoma (1); microcephaly (1); prostate carcinoma (1); squamous cell lung carcinoma (1).